RYR1 (ryanodine receptor 1)
Diseases named in the same sentence as RYR1 in open-access papers (continued):
Sharing a sentence is not in itself a finding about the gene and the disease.
congenital myopathies (continued). "Patients with an RYR1-related congenital myopathy, manifesting as muscle weakness preceding other symptoms as well as other (neuromuscular) diseases resulting in muscle weakness were excluded." (PMID 36751502, 2022). "They presented with a retractile congenital myopathy and displayed histological and MRI findings compatible with an RYR1-related myopathy." (PMID 35741838, 2022). "In conclusion, the present study demonstrates that the combined pharmacological treatment with an FDA-approved DNMT inhibitor and TMP269 improves muscle strength and performance in a mouse model for recessive RYR1 congenital myopathy." (PMID 35238775, 2022). "Early involvement of the sartorius muscle has also been described in patients with mutations in SPEN1, RYR1, TNPO3, and MYH7, in some congenital myopathies like ACTA1, and in myofibrillar myopathies with mutations in DES or CRYAB." (PMID 35286480, 2022). "This study contributes to a novel understanding of the role of RyR1 in myogenic differentiation and related congenital myopathies, and provides a potential target for regulation of muscle characteristics and meat quality." (PMID 35144690, 2022). "This study contributes to a novel understanding of the role of RyR1 in muscle development and related congenital myopathies, and provides a potential target for regulation of muscle characteristics and meat quality." (PMID 35144690, 2022). "Cases with RYR1 variations account for 33 to 59% of patients with congenital myopathies in large cohorts." (PMID 35693006, 2022). "First, histopathology of muscle biopsies from patients harboring RYR1-related congenital myopathies show fiber type I predominance." (PMID 35238775, 2022). "If history of malignant hyperthermia is present, a diagnosis of Native American Myopathy or other congenital myopathies like RYR1 should be considered." (PMID 33827624, 2021). "Several attempts are being made to identify a therapy suited to the objective of treating congenital myopathies, specifically for those that are RYR1 related." (PMID 34827576, 2021). "Pathogenic variants in this gene lead to Ryanodine receptor type 1‐related myopathies (RYR1‐RM); the most common subgroup of congenital myopathies." (PMID 34528764, 2021). "More recently, recessive mutations in RYR1 have been described in patients with CCD or centronuclear myopathy, another congenital myopathy subtype." (PMID 34208776, 2021). "Defects in the RYR1 (OMIM#180901) gene lead to Ryanodine receptor type 1‐related myopathies (RYR1‐RM); the most common subgroup of congenital myopathies." (PMID 34528764, 2021). "Of note, functional studies are needed when mutations are detected in the RYR1 and NEB genes which are associated with congenital myopathies, as variants of uncertain significance are common in these genes due to their large size." (PMID 34193198, 2021). "In a recent study on a large cohort of patients with a recessive congenital myopathy, we have identified the presence of atypical structures, called “dusty cores”, in more than half of the patients with a reduction in RyR1 amount." (PMID 33176865, 2020). "In the present work we focused on the pathophysiology of the exclusive reduction in RyR1 protein expression in muscle, as this situation is frequently observed in patients affected with recessive congenital myopathy." (PMID 33176865, 2020). "Patients with RYR1-related MH and RM exhibit a similar histopathological spectrum, ranging from mild myopathic changes to cores and other features typical of RYR1-related congenital myopathies." (PMID 30788618, 2019). "Screening of the entire RYR1 coding sequence as part of a congenital myopathy sequencing panel is recommended in identification of CNM causative variants." (PMID 30406384, 2018). "Ryanodine receptor type 1-related myopathies (RYR1-RM) are the most common class of congenital myopathies." (PMID 30406384, 2018).
congenital myopathies (continued). "The ryanodine receptor 1-related congenital myopathies (RYR1-RM) comprise a spectrum of slow, rare neuromuscular diseases." (PMID 29556213, 2018). "Screening of the entire RYR1 coding sequence as part of a congenital myopathy sequencing panel is recommended to effectively elucidate the genetic etiology of MmD histopathology." (PMID 30406384, 2018). "Affecting 1/90,000 children in the United States (US), RYR1-related myopathies (RYR1-RM), though rare, comprise the most common congenital myopathies in the US." (PMID 29970108, 2018). "The patient described in this report was recently enrolled in a phase I and phase II efficacy study of N‐acetylcysteine for the treatment of RYR1‐congenital myopathy at the National Institutes of Health in Bethesda, MD." (PMID 28547000, 2017). "While the patient described in this report has a phenotype consistent with autosomal recessive RYR1‐related congenital myopathy, it highlights the importance of this condition in the differential diagnosis for mitochondrial myopathy." (PMID 28547000, 2017). "As next generation sequencing becomes increasingly utilized in the clinic, more and more cases of RYR1‐related congenital myopathy are being uncovered." (PMID 28547000, 2017). "RYR1 congenital myopathies are highly clinically variable and have a broad phenotypic spectrum with overlap with numerous other neuromuscular disorders with diverse molecular etiologies." (PMID 28547000, 2017). "This differs from the defects of calcium handling already shown in other congenital myopathies including disorders linked to BIN1, RYR1 or MTM1 mutations that are centered on defects of triad membrane components, i.e. T-tubules and SR." (PMID 27870637, 2016). "These RyR1-related congenital myopathies are rare muscle disorders (incidence of 6 out of 100,000 births) that exhibit either autosomal dominant or recessive inheritance patterns." (PMID 26793121, 2015). "Both dominant and recessive forms of RYR1-related congenital myopathies have been described and genotype-phenotype correlations have provided insights into likely clinical-functional relationships." (PMID 25476234, 2014). "This is of particular interest for the diagnosis of congenital myopathies, which involve very large genes like RYR1 and NEB as well as genetic and phenotypic heterogeneity." (PMID 23826317, 2013). "In the context of RYR1‐related congenital myopathies the finding that RPL13 is significantly down‐regulated in dHT muscle spindles may be of relevance." (PMID 41091627, 2025). "If these alterations observed in dHT mice also occur in humans, our results could explain at least in part, the skeletal abnormalities, motor delays, joint contractures and gait abnormalities often observed in patients with RYR1 congenital myopathies." (PMID 41091627, 2025). "The more detailed clinical evaluation revealed that the two patients from this family presented some dimorphisms and clinical signals compatible with congenital myopathy, suggesting a possible deleterious role of the duplication in the function of the RYR1 channel." (PMID 41300704, 2025). "Considered the most common form of congenital myopathy, individuals with RYR1-related myopathies may experience skeletal muscle weakness and fatigue, as well as reduced functional capacity." (PMID 40993798, 2025). "Thus, we describe a second patient in whom WGS led to the definitive diagnosis of an RYR1-related congenital myopathy." (PMID 39409197, 2024). "RYR1 and CACNA1S variants are associated with MH and diverse forms of congenital myopathy." (PMID 38647904, 2024). "Pathogenic variants in the ryanodine receptor 1 (RYR1) gene are causative for a wide spectrum of muscular phenotypes, ranging from malignant hyperthermia over mild, non-progressive to severe congenital myopathy." (PMID 39409197, 2024).
congenital myopathies (continued). "RYR1-related myopathies are the most prevalent group of congenital myopathies and have multiple clinical phenotypes, such as symmetric proximal muscle weakness, significant respiratory involvement, King Denborough syndrome, arrhythmias, malignant hyperthermia and so on." (PMID 38649898, 2024). "A total of five patients with RYR1 mutations and diagnosed with a congenital myopathy were compared to five age‐ and gender‐matched controls, as well as five patients with RYR1 variants but without weakness." (PMID 37602753, 2023). "In addition, heterozygous RYR1 variants can be a genetic basis of the King–Denborough syndrome (KDS), a clinical condition characterized by the triad of congenital myopathy, dysmorphic features, and susceptibility to malignant hyperthermia." (PMID 36874254, 2022). "RYR1-related myopathies represent the most common form of congenital myopathy." (PMID 34208776, 2021). "Targeted next-generation sequencing did not detect any genetic mutations related to congenital myopathy, including RYR1, in our patient." (PMID 34193198, 2021). "The patient did not have any pathogenic gene mutations associated with congenital myopathy, including RYR1 and SEPN1 in targeted next-generation sequencing." (PMID 34193198, 2021). "Dominant or recessive RYR1 mutations have been detected in four patients with late-onset atypical PP, both with and without congenital myopathy." (PMID 34208776, 2021). "Additional abnormalities on oxidative staining (generally considered to be more specific for RYR1-related congenital myopathies) were observed in 52% of cases, and included unevenness (or ‘moth-eaten appearance’) (n = 24; 48%), central cores (n = 7; 14%), or multiple minicores (n = 3; 6%)." (PMID 30788618, 2019). "Indeed triads replication and T-tubule dilation has been observed also in dihydropyridine receptor (DHPR)-related congenital myopathy, which is the voltage-gated L-type Ca2+ channel located on the T-tubule-SR interface with RyR1." (PMID 30611313, 2019). "In humans, RYR1 channels are best known for their role in excitation–contraction coupling (ECC), which links motor neuron signaling to skeletal muscle contractions and mutations in the RYR1 gene are a major causative factor of many congenital myopathies." (PMID 31383689, 2019). "Therefore, it has been suggested that RYR1-related myopathies are probably the most frequent form of congenital myopathies in several populations." (PMID 31165076, 2019). "The ability to achieve an early RYR1-RD diagnosis has been further aided by the development of multi-gene congenital myopathy panels which, due to greater availability and decreased cost, should be considered the standard approach when seeking to confirm a specific genetic etiology." (PMID 30155738, 2018). "Pathogenic variants in ryanodine receptor 1 (RYR1, MIM# 180901) are the cause of congenital myopathy with fiber‐type disproportion, malignant hyperthermia susceptibility type 1, central core disease of muscle, multiminicore disease and other congenital myopathies." (PMID 28547000, 2017). "In F045, the severe congenital myopathy with ophthalmoplegia strongly suggested pathogenic variants in RYR1, but no pathogenic variants in RYR1 were identified." (PMID 26247046, 2015). "In a recent review of congenital myopathies treated at a single referral centre, a genetic diagnosis was established in two-thirds of cases and almost 60% of those with a genetic diagnosis had a RYR1-related myopathy." (PMID 25476234, 2014). "Mutations of the type 1 ryanodine receptor (RyR1), a key sarcoplasmic reticulum (SR) Ca2+ release channel almost exclusively expressed in skeletal muscle, are one of the most common causes of non-dystrophic congenital myopathies." (PMID 29701772, 2018).
congenital myopathies (continued). "As an example, proband P144, who suffered from mild high frequency HL and presented with clinical features of congenital myopathy, was found to have a novel, missense variant in a hotspot domain of the RYR1 gene, explaining his primary diagnosis, but not the cause of HL." (PMID 29293505, 2018). "RYR1-RM genetic heterogeneity and the increasing utility of NGS approaches to variant identification, coupled with reduction in sequencing cost, should prompt clinicians and researchers to screen patients for pathogenic variants with congenital myopathy sequencing panels over single gene analysis." (PMID 30406384, 2018). "Recently Schartner and colleagues described a novel class of congenital myopathy associated with recessive and dominant mutations in CACNA1S, the pore-forming subunit of DHPR located on the T-tubule in the proximity of a Ca2+ release channel (ryanodine receptor; RYR1) on the sarcoplasmic reticulum." (PMID 29141652, 2017). "Muscle magnetic resonance imaging (MRI) findings in the same cohort often showed marked muscle hypertrophy corresponding to clinical features, but not the pattern of selective involvement typically seen in RYR1-associated congenital myopathies, in keeping with the divergent clinical phenotypes." (PMID 25929793, 2015). "To test our hypotheses, we used muscle biopsy samples from five patients with congenital myopathy due to RYR1 mutations and compared them with five age‐ and gender‐matched controls and with five patients with RYR1 mutations and rhabdomyolysis/myalgia but without muscle weakness." (PMID 37602753, 2023). "Hence, in the present study, we hypothesized that, in RYR1‐related congenital myopathies, unusual PTMs in particular acetylation and phosphorylation would appear on myosin molecules, more specifically on its myosin heavy chains (MyHCs) rich in lysine, serine, tyrosine, and threonine residues." (PMID 37602753, 2023). "Our results identify RYR1, ATPB2B and miRNA-22 as common transcripts whose expression is decreased in muscles from congenital myopathy patients." (PMID 36196089, 2022). "Ryanodine receptor 1-related myopathies (RYR1-RM) are the most common non-dystrophic congenital myopathies with an estimated prevalence of 1 in 90,000 individuals." (PMID 41301517, 2025). "Ryanodine receptor 1-related myopathies (RyR1-RMs) are the most common non-dystrophic congenital myopathies, with an estimated prevalence of 1 in 90,000 in the United States." (PMID 40243436, 2025). "As RYR1-RM is a congenital myopathy that commonly presents at birth or early childhood, the limited CPET data for a relatively small cohort of children restricts the ability to generalize these findings to the pediatric RYR1-RM population." (PMID 40993798, 2025). "We identified the same heterozygous c.12083C>T transition in RYR1 exon 88 in all nine families, and NGS did not detect other potentially pathogenic variants in known congenital myopathy genes." (PMID 34535181, 2021). "RYR1 should also be considered in dominant and sporadic congenital myopathy patients without evocative cores or central nuclei on the muscle biopsy, especially if the patient manifests neonatal or infancy-onset hypotonia improving over time." (PMID 34535181, 2021). "Ryanodine receptor 1-related myopathies (RyR1-RM) comprise the most common non-dystrophic congenital myopathy, with a prevalence of approximately 1/90,000 in the United States." (PMID 27855725, 2016). "They had a long-standing history of mild generalized weakness, myalgias and cramps with nonspecific histological manifestations, suggesting a congenital myopathy (i.e., variability in fiber size, type 1 fiber predominance) in line with the variable spectrum of RYR1-related phenotypes." (PMID 35741838, 2022).
congenital myopathies (continued). "There is little evidence which links metabolic processes to congenital myopathies, although certain therapies such as N-acetylcysteine have been studied to reduce the deleterious effects of oxidative stress on muscle damage in human recessive RYR1-related myopathies." (PMID 33256785, 2020).
Central core disease (64 papers, 2007 to 2025). Central core disease (CCD) is an inherited neuromuscular disorder characterised by central cores on muscle biopsy and clinical features of a congenital myopathy. "Patients with neuromuscular scoliosis, particularly those with cerebral palsy, central core disease, or multiminicore disease, have a higher likelihood of RYR1 mutations, which predispose them to MH." (PMID 40590017, 2025). "Here, we focus on patients carrying RYR1 variants and muscle histopathology consistent with central core disease (CCD) or multi-minicore disease (MmD)." (PMID 41301517, 2025). "I4898T in RYR1 is one of the most common mutations that give rise to central core disease (CCD), with a variable phenotype ranging from mild to severe myopathy to lethal early-onset core-rod myopathy." (PMID 36450915, 2022). "Mutations in the RYR1 gene, encoding ryanodine receptor 1 (RyR1), are a well-known cause of Central Core Disease (CCD) and Multi-minicore Disease (MmD)." (PMID 35428369, 2022). "Excess RyR1 Ca2+‐leak at rest is a well‐established phenomenon associated with disease states such as central core disease and malignant hyperthermia." (PMID 35703154, 2022). "A large number of mutations in RYR1 are associated with central core disease (CCD), clinically characterized by childhood-onset hypotonia and proximal muscle weakness." (PMID 34359900, 2021). "RYR1 mutations underlie susceptibility to MH and exertional heat stroke but also myopathies such as central core disease (CCD), which cause muscle weakness." (PMID 34705503, 2021). "In humans, RYR1 gene mutations cause several skeletal myopathies, such as central core disease, multiminicore disease and nemaline rod myopathy." (PMID 34884796, 2021). "Nevertheless, RyR1-Q3970 and RyR2-Q3925 are very important residues, since RyR1-Q3970K causes central core disease and RyR2-Q3925E is associated with arrhythmogenic syndrome." (PMID 32040690, 2021). "A majority of variants tested in RYR1 preclinical models were localized to established MH/central core disease (MH/CCD) hot spots." (PMID 32381029, 2020). "The Y524S knock-in mouse has been utilized extensively to investigate the mechanisms behind several phenotypes on the RYR1-RM disease spectrum including MH susceptibility, statin-induced myopathy, and central core disease." (PMID 32381029, 2020). "Mutations in RYR1 are well-linked to a rare genetic neuromuscular disorder known as central core disease that presents with mild to severe muscle weakness." (PMID 32779569, 2020). "For instance, mutations in RYR1, the human ortholog of ryr1b, are well-associated with a rare genetic neuromuscular disorder called central core disease." (PMID 32779569, 2020). "Numerous variants in RYR1 have been identified as the cause of RYR1-RM subtypes, including central core disease (CCD), multi-mini core disease (MmD), centronuclear myopathy (CNM), core-rod myopathy, and congenital fiber type disproportion (CFTD)." (PMID 29970108, 2018). "Mutation of RyR1 or RyR2 causes functional disorders of receptors and induces malignant hyperthermia, central core disease (CCD), catecholaminergic polymorphic ventricular tachycardia, and arrhythmogenic right ventricular dysplasia type 2." (PMID 24130701, 2013). "Here we evaluated the function of the R4892W and G4896V RyR1 mutants, both associated with central core disease (CCD) in humans, in myotubes and in adult muscle fibers." (PMID 23308296, 2013). "The conservation of functionality between RyR1 and UNC-68 is emphasized by an increased sensitivity to the inhalational anesthetic halothane of all tested RyR1 equivalent variants and an increased caffeine sensitivity for variants corresponding to malignant hyperthermia and central core disease." (PMID 35399287, 2022).